ALB (albumin)
Diseases named in the same sentence as ALB in open-access papers (continued):
Sharing a sentence is not in itself a finding about the gene and the disease.
cysticercosis (1 paper, 2024). "To ascertain the impact of cysticercosis on the physiological state of sthe cardiac muscle, we have investigated various physiological parameters, such as the measurement of albumin, total proteins, troponin T, TAC, MDA, and LDH plasma levels." (PMID 38200889, 2024). "Regarding the measured physiological parameters, there were non-significant changes in plasma levels of total protein and albumin in cattle infected with cysticercosis compared with control animals." (PMID 38200889, 2024). "There were non-significant changes in the levels of total proteins and albumin between the control and cattle infected with cysticercosis (p > 0.05)." (PMID 38200889, 2024).
Delayed puberty (1 paper, 2024). Passing the age when puberty normally occurs with no physical or hormonal signs of the onset of puberty. "In our study, we found that diabetic patients with delayed puberty had a higher albumin/creatinine ratio compared to those with normal puberty." (PMID 38724932, 2024).
demyelinating polyneuropathy (1 paper, 2026). Polyneuropathy that is characterized by demyelination of axons. "Cerebrospinal fluid (CSF) analysis demonstrated albumin-cytologic dissociation with a markedly elevated protein level of 485 mg/dL, and nerve conduction studies confirmed a demyelinating polyneuropathy." (PMID 41743127, 2026).
dermatomyositis (1 paper, 2023). Dermatomyositis (DM) is a type of idiopathic inflammatory myopathy characterized by evocative skin lesions and symmetrical proximal muscle weakness. "Gefurulimab (mAbID 1253), a bispecific VH-VH mAb that binds to C5 (to inhibit complement cascade) and albumin (to extend antibody half-life), are currently under clinical development for the treatment of gMG, along with dermatomyositis and proteinuria." (PMID 38140161, 2023).
dermatophytosis (1 paper, 2020). A common fungal infection of the stratum corneum of the skin, hair, or nails by a dermatophyte. "We also found that cats with dermatophytosis had significantly lower hematocrit and serum albumin levels compared with cats without dermatophytosis, suggesting that infected cats were in poorer health." (PMID 33488001, 2020). "Cats with dermatophytosis had significantly lower hematocrit and serum albumin levels than cats without dermatophytosis." (PMID 33488001, 2020). "The median total protein and albumin levels in cats with dermatophytosis were significantly lower than in cats without dermatophyte infection (total protein: 7.45 [6.2-9.5] g/dL vs. 7.7 [6.4-10.5] g/dL, p=0.0055; albumin: 3.1 [2.2-3.8] g/dL vs. 3.4 [2.5-4.1] g/dL, p<0.0001; Figure-5)." (PMID 33488001, 2020).
developmental delays (1 paper, 2016). "Given that astrocytes show developmental delays in FXS, we suggest that the expression levels of albumin and antithrombin III that we detected in Fmr1-KO hippocampal ACM may mirror the expression levels in ACM from the WT hippocampus at earlier time points." (PMID 27242437, 2016).
distal colitis (1 paper, 2023). Particular variety of ulcerative colitis where only the left half of the colon is inflamed. "Inflammation, coagulation and immune indicators like CRP, FC, IL-10, D-D and α1-MG are higher in extensive colitis, and metabolic indicators like LDL-C, HDL-C, TC, GSP and albumin are higher in distal colitis." (PMID 37457023, 2023).
DRESS syndrome (1 paper, 2025). "Albumin administration was avoided after the diagnosis of DRESS syndrome to prevent potential worsening of the condition." (PMID 40843869, 2025).
dysplasia (1 paper, 2023). A usually neoplastic transformation of the cell, associated with altered architectural tissue patterns. "The serum albumin level (g/dl; median (range)) was 4.3 (2.7-5.0) in the cancer/dysplasia group and 3.4 (1.4-5.2) in the refractory group (p<0.01)." (PMID 37641118, 2023).
dysthymia (1 paper, 2013). "A cross-sectional study of elderly women without dementia (11 MDD, 3 dysthymia, 70 non-depressed controls) found an elevated mean CSF-to-serum albumin ratio among those with MDD or dysthymia relative to non-depressed controls (7.1 × 10-3 vs 5.4 × 10-3, age-adjusted P < 0.015)." (PMID 24289502, 2013).
endocrine system neoplasms (1 paper, 2025). "Furthermore, elevated levels of glycated albumin was associated with endocrine system neoplasms." (PMID 40597094, 2025).
ependymoma (1 paper, 2021). A WHO grade II, slow growing tumor of children and young adults, usually located intraventricularly. "0.012), with the highest albumin quotient found on a patient with suspected ependymoma (0.023)." (PMID 34456842, 2021).
erythema multiforme (1 paper, 2025). Erythema multiforme (EM) refers to a group ofhypersensitivity disorders characterized by symmetric red, patchy lesions, primarily on the arms and legs. "Laboratory results showing reducing albumin levels as treatment progresses leading to severely low albumin on presentation with erythema multiforme." (PMID 41209896, 2025).
erythroderma (1 paper, 2024). "In conclusion, BSI should be taken seriously in patients with erythroderma, especially in cases with risk factors such as abnormal temperature (≤36.0 or ≥38.5 °C), chilling, kidney disease, the etiology of drug reactions, elevated CRP (≥32 mg/L) and PCT (≥1.00 ng/ml), and low ALB (≤31.0 g/L)." (PMID 39006018, 2024).
female infertility (1 paper, 2026). Diminished or absent ability of a female to achieve conception. "The red cell distribution width-to-albumin ratio (RAR) is a novel biomarker reflecting inflammation and nutritional status, but its association with female infertility remains unclear." (PMID 41824841, 2026).
femur fracture (1 paper, 2025). A traumatic or pathologic injury to the femur in which the continuity of the femur is broken. "The ROC analysis revealed that the APACHE II score, albumin levels, and hospital stay duration were the most effective predictors of mortality in postoperative femur fracture patients in the ICU." (PMID 40142349, 2025).
Fibroadenoma (1 paper, 2024). A benign tumor of the breast characterized by the presence of stromal and epithelial elements. "For both BC and fibroadenomas, the factors dependent on BMI were pH, calcium concentration, urea, albumin, imidazole compounds and GGT activity." (PMID 39452912, 2024).
Flavivirus Infections (1 paper, 2017). Infections with viruses of the genus FLAVIVIRUS, family FLAVIVIRIDAE. "The use of bovine serum albumin in infectious meals provides an opportunity to evaluate the role of serum albumin during the process of flavivirus infection in mosquitoes." (PMID 28796799, 2017).
floor-of-mouth tumours (1 paper, 2018). "Although the conventional use of 99mTc-nanocolloidal albumin and SPECT/CT may result in the detection of additional SLN compared to gamma camera imaging, detection of level I lymph nodes in floor-of-mouth tumours remains challenging." (PMID 29445878, 2018).
folate deficiency (1 paper, 2022). A nutritional condition produced by a deficiency of FOLIC ACID in the diet. "Other risk factors for MTX toxicity include high doses of MTX, renal impairment, nonsteroidal antiinflammatory drugs, age over 55 years, folate deficiency, low serum albumin, and any drug that displaces MTX from its protein." (PMID 36443884, 2022).
foot and mouth disease (1 paper, 2018). A viral infectious disease that results in infection in cattle and swine, has material basis in foot-and-mouth disease virus, which is transmitted by contaminated fomites, or transmitted by ingestion of food contaminated with infected meat or animal products. "Australia is restricted to importing bovine serum albumin (BSA) from New Zealand, Canada and the United States, to avoid the risks of foot and mouth disease." (PMID 29361748, 2018).
gallbladder polyps (1 paper, 2025). "However, among diabetic individuals, due to the limited sample size, only ALB, WBC, HbA1c, and gallbladder polyps exhibited significant differences between the two groups." (PMID 40125519, 2025).
gastric neuroendocrine tumor (1 paper, 2023). "ALB was also confirmed as a predictive biomarker of LNM in patients with gastric neuroendocrine tumor." (PMID 37081978, 2023).
gastroparesis (1 paper, 2025). Paralysis of the muscles of the stomach wall resulting in delayed emptying of the gastric contents into the small intestine. "Moreover, critically ill stroke patients often experience impaired consciousness, dysphagia, gastroparesis, and intestinal barrier dysfunction, all of which contribute to nutrient malabsorption and reduced albumin levels." (PMID 40969611, 2025).
generalized epilepsy (1 paper, 2024). Epilepsy that is characterized by generalized seizure types and may have typical interictal and/or ictal EEG findings that accompany generalized seizure types (for example generalized spike-wave). "The IVW method showed that ALB was significantly associated with a decreased risk of generalized epilepsy (OR = 0.723, 95% CI 0.619–0.845, P = 4.26E-05)." (PMID 40217387, 2024). "Glutathione transferase is associated with increased risk of generalized epilepsy (OR = 1.055), while albumin is associated with decreased risk of generalized epilepsy (OR = 0.723)." (PMID 40217387, 2024). "GST is associated with an increased risk of generalized epilepsy, while ALB is associated with a decreased risk of generalized epilepsy." (PMID 40217387, 2024). "In conclusion, in this bidirectional MR study, we showed a significant causal relationship between ALB and generalized epilepsy." (PMID 40217387, 2024).
geographic atrophy (1 paper, 2013). "Mice immunized with CEP adducted albumin develop focal changes in the RPE resembling those in geographic atrophy, with animals with the most severe lesions also exhibiting significantly elevated CEP autoantibody titer." (PMID 24098476, 2013).
GI dysfunctions (1 paper, 2022). "Simple biochemical parameters such as albumin, hemoglobin, and TLC have long been identified as indicators of nutrient malabsorption associated with GI dysfunctions." (PMID 35755035, 2022).
Gliosis (1 paper, 2016). Gliosis is the focal proliferation of glial cells in the central nervous system. "In our quantitative analysis of normal cortex, we noted a positive correlation between T2 and gliosis (GFAP) and albumin leakage and T1, suggesting that 9.4T MRI signals may be influenced by subtle reactive cellular changes." (PMID 26268959, 2016).
GM1 gangliosidosis (1 paper, 2011). A rare lysosomal storage disorder characterized biochemically by deficient beta-galactosidase activity and clinically by a wide range of variable neurovisceral, ophthalmological and dysmorphic features. "This barrier damage was confirmed by vascular leakage of Evans Blue and albumin resulting from endothelium damage in MPS III B mice, similar to extravasation of Evans Blue and endogenous IgG findings in mouse models of Sandhoff disease and GM1 gangliosidosis." (PMID 21408219, 2011).
H. pylori (1 paper, 2025). "Consistent with the findings from the overall population, significant differences were observed in age, BMI, TC, ALB, WBC, ESR, and HbA1c levels between the H. pylori-infection and non-infection groups among non-diabetic individuals." (PMID 40125519, 2025).
hemorrhagic cystitis (1 paper, 2025). Inflammation of the bladder resulting in bloody urine. "The incidence of positive urinary occult blood and hemorrhagic cystitis in TA-TMA and grade III-IV aGVHD groups were higher than those in aGVHD I-II group, and the levels of platelet and serum ALB in TA-TMA and grade III-IV aGVHD groups were lower than those in grade I-II aGVHD group." (PMID 41438980, 2025).
hippocampal atrophy (1 paper, 2024). "In terms of laboratory findings, patients in the hippocampal atrophy group had higher levels of serum urea, serum creatinine, glucose, and homocysteine, but lower levels of eGFR, albumin, ALT and hemoglobin." (PMID 38895693, 2024).
Hurler syndrome (1 paper, 2019). Hurler syndrome is the most severe form of mucopolysaccharidosis type 1 (MPS1), a rare lysosomal storage disease, characterized by skeletal abnormalities, cognitive impairment, heart disease, respiratory problems, enlarged liver and spleen, characteristic facies and reduced life expectancy. "Previous studies have demonstrated the expression of therapeutic transgenes from the albumin locus in the liver;7 here, we test the therapeutic benefit of inserting a human IDUA (hIDUA) transgene at the albumin locus in hepatocytes using the murine model of Hurler syndrome." (PMID 30528089, 2019).
Hyperhidrosis (1 paper, 2023). Abnormal excessive perspiration (sweating) despite the lack of appropriate stimuli like hot and humid weather. "Twenty subjects with primary axillary hyperhidrosis were enrolled and injected subcutaneously with either BoNT-B (Myobloc®) (2500 U, or 0.5 mL, per axilla) or 0.5 mL vehicle (100 mM NaCl, 10 mM succinate, and 0.5 mg/mL human albumin) into bilateral axillae." (PMID 36828461, 2023).
hyperlipoproteinemia (1 paper, 2023). An elevated concentration of lipoproteins. "In patients with hyperlipoproteinemia, fentanyl demonstrated enhanced binding to whole plasma; this was attributed to the presence of elevated lipoprotein fractions, since the level of fentanyl binding to albumin was not altered." (PMID 36646965, 2023).
hypogammaglobulinemia (1 paper, 2006). "Normal B cell function, low albumin, and the intermittent history of significant lymphedema suggested the possibility of protein loss as the explanation for the hypogammaglobulinemia." (PMID 17194183, 2006).
IgA vasculitis (1 paper, 2021). "As biomarkers for IgA vasculitis, the severity of IgA vasculitis is associated with neutrophil/lymphocyte rate, serum neopterin and ischemia-modified albumin levels, skin miRNA-223-3p expression, and serum and urine levels of NGAL, KIM-1, and L-FABP." (PMID 34299162, 2021).
inner ear disorder (1 paper, 2014). A non-neoplastic or neoplastic disorder affecting the inner ear. "We considered that the bovine serum albumin nanoparticles may have potential applications in the field of local drug delivery in the treatment of inner ear disorders." (PMID 25114637, 2014).
Intellectual disability (1 paper, 2024). "In the multivariate analysis, the following factors were included: intellectual disability, motor dysfunction, serum albumin, serum ALP, blood type, and PTA." (PMID 38587684, 2024). "However, they showed statistically significant differences in motor dysfunction, intellectual disability, serum albumin, serum ALP, and PTA." (PMID 38587684, 2024).
intestinal cancer (1 paper, 2024). "The role of albumin (ALB) has not been deeply explored in the context of altered dietary iron and intestinal cancer." (PMID 38732562, 2024).
intestinal lymphangiectasia (1 paper, 2022). Dilatation of the intestinal lymphatic system usually caused by an obstruction in the intestinal wall. "In the case of DC, considering that albumin was found only in this group and not in the healthy one, it is possible to hypothesize that its presence may be due to the damage associated with GI disturbances, as is also assumed for the dogs suffering from intestinal lymphangiectasia." (PMID 36139251, 2022).
intracranial hypertension (1 paper, 2024). A finding characterized by increased cerebrospinal fluid pressure within the skull. "With the increase of BBB permeability, a large amount of albumin in the blood is secreted to the ipsilateral BBB, causing intracranial hypertension to aggravate brain edema and acute intracranial hemorrhage after thrombolysis." (PMID 38364236, 2024).
intracranial meningioma (1 paper, 2023). A meningioma that arises within the cranial cavity. "Higher preoperative albumin concentration was identified as an independent risk factor for IBL greater than 691.43 ml in patients undergoing resection of intracranial meningioma in the present study." (PMID 37682850, 2023). "Larger tumor size, higher preoperative albumin concentration and higher preoperative platelet count were identified as independent risk factors for greater IBL in resection of intracranial meningioma." (PMID 37682850, 2023). "Multivariate analysis revealed that greater 2D tumor area (p < 0.001), higher preoperative albumin concentration (p = 0.029) and higher preoperative platelet count (p = 0.03) were independent risk factors for greater IBL in resection of intracranial meningioma." (PMID 37682850, 2023). "In the present study, larger tumor size, higher preoperative albumin concentration and higher preoperative platelet count were identified as significant independent risk factors for greater IBL in adult patients undergoing resection of intracranial meningioma." (PMID 37682850, 2023). "Therefore, the effect of serum albumin on platelet and coagulation seemed various and complicated, which should be considered when fluid therapy was required during removal of intracranial meningioma." (PMID 37682850, 2023). "Large tumor size, higher preoperative albumin concentration and higher preoperative platelet count were identified as independent risk factors for significant IBL in adult patients undergoing resection of intracranial meningioma." (PMID 37682850, 2023).
intraepithelial neoplasia (1 paper, 2022). A precancerous neoplastic process that affects the squamous, glandular, or transitional cell epithelium without evidence of invasion. "In conclusion, our study revealed that low platelet and albumin levels were probably unfavorable prognostic factors in intraepithelial neoplasia of the stomach after ESD." (PMID 36344959, 2022).
Kidney Cyst (1 paper, 2019). Abnormal fluid filled sac within the kidney, either acquired or congenital. "Effects of increased water intake on body weight, kidney weight, kidney cyst area, and serum glucose and albumin." (PMID 30601830, 2019).
Klebsiella Infections (1 paper, 2021). Infections with bacteria of the genus KLEBSIELLA. "Although the pathophysiological link between low albumin levels and Klebsiella infection is unclear, this is an informative and readily widely available predictor, ordered by the physician in >90% of the cohort." (PMID 34160237, 2021). "The association between low albumin levels and infection (OR, 2.0 [CI, 1.15 to 3.48]) (P = 0.013) was also previously observed for Klebsiella infections in the ICU, including both colonized and noncolonized patients." (PMID 34160237, 2021).
Klebsiella pneumoniae (1 paper, 2013). "Diabetic PLA patients with poorer glycemic control had significantly higher Klebsiella pneumoniae (KP) infection rates, lower albumin levels, and longer hospital stays than those with suboptimal and good glycemic control." (PMID 23724053, 2013).
latent infection (1 paper, 2015). "The difference between total serum protein and albumin, i.e. the gamma gap, is a frequently used clinical screening measure for both latent infection and malignancy." (PMID 26629820, 2015).
Lewis lung carcinoma (1 paper, 2015). "Selective latex angiography revealed that the Lewis lung carcinoma implant model and the Albumin-Cre/WW45fl/fl model reproduced conventional angiography findings of human HCC." (PMID 26131558, 2015).
lipidosis (1 paper, 2024). "Serum concentrations of albumin and urea were lower in the Severe lipidosis group in the univariable analysis but did not remain significant in the final multivariable regression model." (PMID 39057982, 2024).
lipodystrophy (1 paper, 2023). A congenital or acquired disorder characterized by abnormal loss or redistribution of the adipose tissue in the body. "While responses of mice and humans to a metabolic challenge are not always identical, it is worth noting that albumin knockout mice have normal body weight and low lipid storage in the liver, thus not suffering from a lipodystrophy phenotype." (PMID 36979342, 2023).